IL6R (interleukin 6 receptor)
Diseases named in the same sentence as IL6R in open-access papers (continued):
Sharing a sentence is not in itself a finding about the gene and the disease.
metabolic syndrome (16 papers, 2011 to 2025). A cluster of metabolic risk factors for CARDIOVASCULAR DISEASES and TYPE 2 DIABETES MELLITUS. "Some studies revealed that polymorphisms of IL-6R increased the risk of ischemic stroke in patients with metabolic syndrome and were associated with the neurologic status of ischemic stroke patients." (PMID 38827573, 2024). "In summary, IL-6R rs8192284 A/C and rs2229238 C/T variants associated with dyslipidemia were presented among young adolescents, especially in girls, in Taiwan." (PMID 21835044, 2011). "Our IL6R polymorphism results suggest that, during the treatment of patients with active RA with tocilizumab, rs4845625 is associated with the development of dyslipidemia, and rs11255618 and rs4329505 are associated with the development of hematological effects." (PMID 36675722, 2022). "In contrast, the minor alleles of the IL-6R SNPs were related to high dyslipidemia risk in girls." (PMID 21835044, 2011). "Another suggested explanation is that dyslipidemia is mediated by the direct effect of IL-6 levels, raised through the blockage of IL-6R on administering tocilizumab." (PMID 36675722, 2022). "Consistent with the lipolytic effect of IL-6, inhibition of IL-6R using tocilizumab in RA patients leads frequently to weight gain and dyslipidemia by increasing the levels of cholesterol and triglycerides and therefore potentially increasing CVR." (PMID 29137196, 2017). "The gender-specific role of IL-6R SNPs in the pathology of dyslipidemia should be further investigated." (PMID 21835044, 2011). "The IL-6R rs8192284 A/C and rs2229238 C/T variants are associated with dyslipidemia in girls, but not in boys." (PMID 21835044, 2011). "Importantly, both GCKR and IL6R were reported in metabolic syndrome." (PMID 38785970, 2024). "Therefore, it is plausible that alterations in the IL6R pathway may influence the development of dyslipidemia." (PMID 38001504, 2023). "In the Women’s Genome Health Study, metabolic-syndrome related genes, such as LEPR, HNF1A, IL6R, and GCKR, were correlated to CRP expression and inflammation." (PMID 35845045, 2022). "Dyslipidemia is a known adverse effect of tocilizumab (TCZ), an anti-interleukin-6 receptor antibody used in RA treatment." (PMID 31540528, 2019).
hepatocellular carcinoma (15 papers, 2013 to 2024). A malignant tumor that arises from hepatocytes. "In mouse models of hepatocellular carcinoma, miR-124 is involved in an inflammatory feedback loop where it suppresses the expression of IL-6R and reduces STAT3 activation in transformed cells." (PMID 23940556, 2013). "The expression of both IL-6 and IL-6R within the hepatocellular carcinoma (HCC) microenvironment was found to contribute to the recurrence of tumors following surgery." (PMID 37892997, 2023). "In hepatocellular carcinoma, circHIPK3 can act as a sponge to absorb miR-124 and upregulate the downstream target genes IL6R and DXL2 through a competing endogenous RNA (ceRNA) mechanism, thereby promoting the proliferation of hepatoma cells." (PMID 33824287, 2021). "Multiple miR-125b targets were found to be upregulated in hepatocellular carcinoma, including BCL2, BCL2 like 2 (Bcl-W), myeloid cell leukemia sequence 1 (Mcl-1), interleukin-6 receptor (IL6R), lin-28 homolog B (LIN28B) and placenta growth factor (PIGF)." (PMID 24774301, 2014). "IL6R increased BCL-2 and STAT3 in hepatocellular carcinoma (HCC)." (PMID 31484561, 2019). "This study aimed to explore the responses to the interleukin-6 (IL-6)/soluble interleukin-6 receptor (sIL-6R) complex in peritumoral endothelial cells (PECs) and tumor endothelial cells (TECs), as well as determine the signaling pathways in the angiogenesis of hepatocellular carcinoma (HCC)." (PMID 26525581, 2015).
pneumonia (14 papers, 2018 to 2025). An acute, acute and chronic, or chronic inflammation focally or diffusely affecting the lung parenchyma, caused by an infection in one or both of the lungs (by bacteria, viruses, fungi, or mycoplasma.). "IL-6 signaling downregulation via IL6 perturbation was associated with a lower risk of pneumonia hospitalization, in contrast to associations of IL6R missense variants with a higher risk of bacterial infections." (PMID 40858837, 2025). "Both FOCUS and eQTL annotation supported that downregulation of IL6R would be risk increasing for pneumonia, however, the odds increasing allele of the IL6R locus in this GWAS was associated with increased IL-6R protein levels." (PMID 35768473, 2022). "Interestingly however, IL6-mediated genetic downregulation of IL-6 signaling was associated with lower risk of hospital admission due to pneumonia, in contrast to a higher risk linked to IL6R perturbation." (PMID 40858837, 2025). "Importantly, our MR analysis revealed contrasting effects of genetically proxied IL-6R inhibition on pleural infection (reduced risk) vs. pneumonia (increased risk, OR 1.21, 95% CI 1.07–1.38)." (PMID 40819633, 2025). "This cluster contains an IV mapped to the IL6R gene which this study indicates has a protective effect on pneumonia susceptibility, supporting proceeding analyses that suggest IL6R inhibition may be odds increasing for pneumonia." (PMID 35768473, 2022). "Additionally, results were replicated using a non-overlapping population from the deCODE study to derive the IL-6R IV and this confirmed a similar magnitude and direction of association with risk of empyema (OR 0.26 95% CI 0.13–0.51) and pneumonia (OR 1.19 95% CI 1.00–1.42)." (PMID 40819633, 2025). "To determine if inflammation influenced the risk of incident pneumonia in CHIP carriers, we added an interaction term for a common SNPs in the IL6 receptor gene (IL6R [rs2228415]), which reduces IL6 signaling." (PMID 38573824, 2024). "In the future, the use of IL-6R and G-CSFR antagonists in the treatment of influenza-associated pneumonia patients with high levels of IL-6 and G-CSF needs to be explored." (PMID 35382755, 2022). "In summary, it appears from these data that inhibition of IL6R would increase the odds of pneumonia, although further study is needed, particularly as this is a GWAS of susceptibility, not pneumonia severity." (PMID 35768473, 2022). "Based on these data, COVID19 patients with pneumonia were also treated with drugs directed against IL-6 receptor (IL6R), such as tocilizumab, with promising results." (PMID 32917282, 2020). "Notably, there was a differential effect between IL6 and IL6R perturbation on hospitalization due to pneumonia." (PMID 40858837, 2025). "Similarly, circ_0012535 exacerbates pneumonia progression in fetal lung fibroblasts by targeting the miR-338-3p/IL6R signaling pathway to promote cell apoptosis and inflammatory responses." (PMID 41105618, 2025). "Tocilizumab, an anti-interleukin-6 receptor, administrated during the right timeframe may be beneficial against coronavirus-disease-2019 (COVID-19) pneumonia." (PMID 33080877, 2020). "Unlike IL6R missense variants linked to bacterial infections, the IL6 instrument was associated with lower risk of pneumonia hospitalization." (PMID 40858837, 2025).
viral infection (14 papers, 2011 to 2025). "Moreover, a number of cytokines, including IL-6, IL-6R, IL-21 and IL-4, have been implicated in shaping immune responses after viral infection." (PMID 27447555, 2016). "Therefore, the intimate relationship between viral infection, IFN/TNF/IL-6R/STAT1expression, and the associated signaling pathway is valuable in elucidating the mechanism of virus-associating CRC." (PMID 32258125, 2020). "Chronic hepatitis B or C viral infections are major risk factors of HCC, and up-regulation of IL6R could significantly differentiate HCC from hepatitis patients." (PMID 22942733, 2012). "At the early stages of virus infection i.e. at 4 hpi, we found up-regulation of immune genes like TNF-α3, EGR-1, IL6R, v-FOS, v-JUN." (PMID 21439068, 2011). "Interestingly, we observed in mouse PCLS no induction of Il6r or Il6st gene expression upon virus infection, but BRO upregulated both Il6r and Il6st, as well as Adam17 in the presence but also in the absence of virus." (PMID 31067687, 2019). "In conclusion, our results show that blockade of IL-6R in hospitalized patients with COVID-19 pneumonia produces only minimal changes in HDL-C levels, suggesting that the viral infection, and not IL-6–mediated inflammation, is the main driver of HDL-C depression." (PMID 38795859, 2024). "It is also possible that IL-6 may act on other sites not blocked by α-IL-6R mAb, and that this may yield a potential advantage of using α-IL-6 mAb to treat CRS brought about by a viral infection." (PMID 33071786, 2020).
glioblastoma (13 papers, 2015 to 2023). The most malignant astrocytic tumor (WHO grade IV). "We found a single, currently suspended clinical trial of the IL6R antibody tocilizumab for gliomas and glioblastoma treatment (NCT04729959), trials for metastatic breast cancer (NCT03135171), non-small lung cancer among others (NCT04940299)." (PMID 37006265, 2023). "Consistent with the literature, expression of IL6R has strong prognostic value in glioblastoma and in lung adenocarcinoma." (PMID 37006265, 2023). "Finally, IL6 and IL6R genes were both upregulated in glioblastoma, head and neck, kidney clear cell carcinoma, and testicular cancer." (PMID 34576335, 2021). "Analysis of the TCGA dataset revealed that IL-6 and IL-6R mRNA levels were significantly higher in mesenchymal subtype and IDH-wildtype glioblastoma." (PMID 38188300, 2023). "This is consistent with studies in glioblastoma showing that inhibition of IL-6 or its receptor, IL-6Rα, diminishes STAT3 activation and, in turn, the number of glioblastoma stem cells." (PMID 26880966, 2016). "Different types of cyto-chemokines are involved in the crosstalk between hAT-MSCs and BTICs (medulloblastoma and AT/RT: CXCR4/SDF-1, CCR5/RANTES, IL6R/IL-6 and IL8R/IL8; glioblastoma: CXCR4/SDF-1, IL6R/IL-6, IL8R/IL-8 and IGF1R/IGF-1)." (PMID 26076490, 2015). "Furthermore, BACE1 reduced the phagocytosis of tumor cells in glioblastoma by activating the tumor-promoting macrophages via cleaving interleukin-6 receptor (IL-6R) and activating IL6/sIL-6R/STAT3 signaling." (PMID 38201438, 2023). "This phenotype required BACE1 cleavage of IL-6R, which is expressed in macrophages, but not neurons, making BACE1 a potential drug target for glioblastoma." (PMID 36810097, 2023). "Moreover, Kammerer and co-workers observed significant upregulation of inflammation-related genes, including CXCL2, CXCL3, IL1A, and IL6 receptor (IL6R)) after non-lethal 5-ALA-PDT in a panel of prostate and glioblastoma cell lines." (PMID 26705830, 2015).
Hypertension (13 papers, 2018 to 2025). The presence of chronic increased pressure in the systemic arterial system. "According to our cellular data, such loss in β-adrenergic responsiveness would upregulate NCX under tachycardic pacing stress, an effect likely potentiated by the mechanical stress to individual myocytes caused by hypertension, thus together leading to IL6R upregulation." (PMID 35884952, 2022). "Strikingly, we identified the IL6R pathway as one of the most affected signaling cascades in hypertension-induced cardiac remodeling, which is characterized by simultaneous β-adrenergic receptor 1 downregulation and NCX upregulation." (PMID 35884952, 2022). "The potential role of ADAM17-mediated shedding of IL-6R and its role in IL-6 trans-signaling-mediated inflammation and its impact on hypertension needs investigation." (PMID 32848763, 2020). "To test the pathophysiological relevance of the newly identified role of β-adrenergic stimulation in preventing increased NCX expression and IL6R signaling, we further investigated the potential impairment of this pathway in hypertension-induced cardiac remodeling." (PMID 35884952, 2022). "Patients who had improved hypertension 6 months after surgery presented with increased expression levels of the inflammasome activation components (ASC, P2X7, and IL18R), cytokines (CCL8, CXCL2, IKKA, and IL6R), NOD-like receptors (NLRP1), and cell cycle/DNA regulators (TGFb)." (PMID 37867510, 2023).
periodontitis (13 papers, 2015 to 2024). An acute or chronic inflammatory process that affects the tissues that surround and support the teeth. "In this study, we tested the biological effect of IL-6 signaling downregulation on the risk of periodontitis simulating the effect of monoclonal antibodies that target IL-6R by blocking both IL-6 classic and trans-signaling." (PMID 37342352, 2023). "Treatment with anti-IL-6 receptor (IL-6R) antibody significantly inhibited the generation of exFoxp3TH17 cells as well as bone loss in periodontitis-induced mice." (PMID 29453398, 2018). "Moreover, such treatment reduced alveolar bone resorption and attachment loss suggesting that IL-6R blockade may be a promising approach for periodontitis." (PMID 39253090, 2024). "Consistently, treatment of experimental ligature-induced periodontitis by systemic administration of the humanized monoclonal IL-6R antibody tocilizumab suppressed inflammatory cell recruitment, Th17 cytokines and impaired RANKL expression." (PMID 39253090, 2024). "IL6R expression was overall stronger in the periodontitis groups than the non-periodontitis groups; however, it was even more intense in the DP group, particularly in the basal layer of the epithelium and connective tissue." (PMID 38241313, 2024). "Our results identified IL-6R as a potential drug target to prevent the development of periodontitis and as a host modulating adjunctive periodontitis therapy." (PMID 37342352, 2023). "HGFs do not express enough IL-6R on the cell surface to adequately bind IL-6 but do express gp130, which can bind to the IL-6/sIL-6R complex in the presence of sIL-6R, such as in periodontitis." (PMID 36834667, 2023). "A clinical study showed that tocilizumab, an IL-6R inhibitor, significantly ameliorated periodontal inflammation." (PMID 29453398, 2018). "Further studies are necessary to determine the beneficial effect of IL‐6R blockade on periodontitis in a larger group of patients and controls." (PMID 29744142, 2015). "P. gingivalis may affect the progression of BPH through IL-6/IL-6R inflammation and Akt signaling pathways, suggesting that the distal metastasis of oral pathogens is a possible mechanism for periodontitis to promote BPH." (PMID 38764065, 2024). "Hypermethylation was found in TLR regulators genes: MAP3K7, MYD88, IL6R, RIPK2, FADD, IRAK1BP1, and PPARA in early stages of periodontitis, while advanced stages presented hypomethylation of these genes." (PMID 36233348, 2022). "IL6, IL6R, IFNG, PTGS2, SOCS1, and TNF were identified as candidate genes that have been assessed for DNA methylation in periodontitis." (PMID 32867386, 2020). "IL6R blockade may have a more beneficial effect for T2D with lower hba1c levels in AFR vs EUR, as well as potential beneficial effects for glaucoma, keratoconjunctivitis, and periodontitis." (PMID 38580710, 2024).
uveitis (13 papers, 2017 to 2025). An inflammatory process affecting a part of or the entire uvea. "Anti-TNF-α agents (e.g., infliximab) achieve corticosteroid sparing control in refractory uveitis (adult and pediatric cohorts), while anti-IL-6R (tocilizumab) is effective for uveitic cystoid macular edema and in juvenile idiopathic arthritis associated uveitis refractory to anti-TNF therapy." (PMID 41169366, 2025). "Genes associated with the risk of developing uveitis include ERAP1, intergenic region 2p15, IL23R, IL10-IL19, IL18R1-IL1R1, IL6R, KIF21B, and EYS." (PMID 35629038, 2022). "The humanized anti-human IL-6R mAb, Tocilizumab, is effective to treat refractory uveitis and potent new therapeutic for other ocular diseases." (PMID 29440661, 2018). "Therapeutically, interventional human evidence now supports immunity as both driver and target: anti-VEGF re-seals leaky barriers, complement inhibition slows geographic atrophy, steroid implants suppress inflammatory oedema, and anti-TNF/IL-6R biologics improve refractory uveitis." (PMID 41394857, 2025). "There is emerging evidence that targeting IL-6R can also be efficacious in treating severe non-infectious uveitis, both idiopathic and associated to JIA." (PMID 36979992, 2023). "However, in vivo, soluble IL-6R has been detected in the aqueous humor of eyes with uveitis, and it is plausible that if this is present in higher concentrations than detected in our cultures, inner BRB disruption still may ensue." (PMID 31667008, 2019). "Tocilizumab, a monoclonal antibody that inhibits the interleukin-6 receptor, is a promising option for treating non-infectious uveitis, route of administration may be intravenous or subcutaneous." (PMID 39062219, 2024).
Immunodeficiency (12 papers, 2017 to 2025). Failure of the immune system to protect the body adequately from infection, due to the absence or insufficiency of some component process or substance. "On the other hand, therapeutic IL-6R antibodies can cause dermatitis, and inborn errors in IL6R cause immunodeficiency, atopy including atopic dermatitis, elevated IgE levels, and abnormal inflammatory responses." (PMID 40461723, 2025). "However, recent literature has reported that deficiency of IL-6R may lead to immunodeficiency and the occurrence of abnormal inflammatory responses." (PMID 39253091, 2024). "The latest IUIS classification has redefined DOCK8 deficiency as a combined immunodeficiency, and other genes like ZNF341 and components of the IL-6 pathway (IL6ST, IL6R) can cause HIES-like phenotypes." (PMID 41458089, 2025). "Our results may be viewed as another way of reversing innate immunodeficiency by adaptive immunity using Treg cells and anti-IL-6R." (PMID 29386580, 2018). "Genes (IL6R, AHSG, and other cluster-specific DEGs) in HCC4 (cluster 4) were enriched in phosphatase activity and downregulated process related to immune disorders." (PMID 33462196, 2021). "Therefore, MTX could better neutralize activated and proliferating CD73+ Teff, while anti-IL-6R might target CD73neg Teff; their combined action provide a better regulation of the overall hyper activated Teff population in the contexts of auto-immune disorders." (PMID 31684171, 2019). "Agents targeting ICOSLG, IL6R, and CD28 are broadly applied in managing immune system diseases." (PMID 40868097, 2025).